LHB (luteinizing hormone subunit beta)
Diseases named in the same sentence as LHB in open-access papers (continued):
Sharing a sentence is not in itself a finding about the gene and the disease.
cryptorchidism (1 paper, 2025). The failure of one or both testes of a male fetus to descend from the abdomen into the scrotum during the late part of pregnancy. "In humans, loss-of-functionmutations in the LH β-subunit gene (LHB) resulted in lowtestosterone, undermasculinisation, cryptorchidism, micropenis, and azoospermia,even when FSH levels remain normal." (PMID 40833973, 2025).
Cushing syndrome (1 paper, 2025). Cushing's syndrome (CS) encompasses a group of hormonal disorders caused by prolonged and high exposure levels to glucocorticoids that can be of either endogenous (adrenal cortex production) or exogenous (iatrogenic) origin. "LC-TPIT primarily includes genes implicated in Cushing syndrome (e.g., POMC, EGFR), and LC-SF1 is enriched for components of the GnRH signaling pathway (e.g., LHB, FSHB)." (PMID 41253784, 2025).
hepatocellular carcinoma (1 paper, 2024). A malignant tumor that arises from hepatocytes. "It has been demonstrated that the proliferation induced by stable LHB expression is associated with increased G1/S cell cycle progression and apoptosis resistance mediated by SRC kinase activation, as established using clinical specimens of hepatocellular carcinoma." (PMID 39234106, 2024).
hypogonadotropic hypogonadism (1 paper, 2019). Abnormal ovarian or testicular function due to insufficient hormonal stimulation from the hypothalamic-pituitary axis. "The LHB sequence was analyzed for a 30-year-old patient who was suffering from hypogonadotropic hypogonadism, and the patient was treated with human chorionic gonadotropin (hCG), resulting in adequate spermatogenesis." (PMID 31905946, 2019).
liver disease (1 paper, 2025). "This review synthesizes mechanisms by which hepatitis B surface gene mutations drive immune escape and LHB trafficking defects, which lead to ER stress and UPR response, thus resulting in liver disease." (PMID 40733591, 2025).
melanoma (1 paper, 2021). A malignant, usually aggressive tumor composed of atypical, neoplastic melanocytes. "The result demonstrated that CCLB (P = 0.018), INHA (P < 0.001), and NDRG1 (P = 0.001) were significantly upregulated in metastatic melanoma, while LHB (P = 0.001) was significantly downregulated when compared with primary melanoma." (PMID 33688507, 2021).
mental disorder (1 paper, 2024). A disease that has its basis in the disruption of mental process. "In summary, our anatomical description reinforces the functional role of the LHb as a key hub in complex behaviors and mental disorders." (PMID 38654275, 2024).
Miscarriage (1 paper, 2025). A pregnancy that ends at a stage in which the fetus is incapable of surviving on its own, defined as the spontaneous loss of a fetus before the 22th week of pregnancy. "In general, though little is known about CGB SNPs and their possible association with miscarriage, LHB SNPs are linked to human phenotypic variations that might mildly contribute to the pathogenesis of reproductive diseases, such as polycystic ovary syndrome (PCOS)." (PMID 40001128, 2025).
post-traumatic stress disorder (1 paper, 2023). An anxiety disorder precipitated by an experience of intense fear or horror while exposed to a traumatic (especially life-threatening) event. "This offers a framework in which LHb aberrant activity may produce cue generalization – a behavioural feature of disorders including post-traumatic stress disorders, for instance." (PMID 37414924, 2023).
preeclampsia (1 paper, 2014). Preeclampsia is a hypertensive disorder of pregnancy that is characterized by new-onset hypertension with proteinuria presenting after 20 weeks of gestation, and depending on mild or severe forms may initially present with severe headache, visual disturbances, and hyperreflexia. "In accordance with the altered trophoblast pathophysiology in early-onset preeclampsia, many of the most differentially regulated genes in women with preeclampsia (LEP, CGB, LHB, INHA, SIGLEC6, PAPPA2, and FLT1) have predominant or unique expression in the syncytiotrophoblasts." (PMID 24991435, 2014).
Pruritus (1 paper, 2023). Pruritus is an itch or a sensation that makes a person want to scratch. "Based on the fact that LHb plays a key role in processing and regulating itch information above, we finally investigate how the itchy signals are transmitted to the LHb." (PMID 37370111, 2023). "Nevertheless, manipulation of the-LHb centered circuits will be required to determine their roles in itch in the future." (PMID 37370111, 2023). "Together, these findings reveal the involvement of LHb in processing both the sensational and emotional components of pruritus and may shed new insights into itch therapy." (PMID 37370111, 2023). "In this study, we examined the population activity of LHb neurons using in vivo fiber photometry in responses to pruritogens and chronic itch in freely moving mice, and assessed the behavioral consequences following chemogenetic inhibition of GluLHb neurons in models of both acute and chronic itch." (PMID 37370111, 2023). "Furthermore, we explored the role of LHb in affective component of itch using the CPA paradigm." (PMID 37370111, 2023).
psychiatric disorder (23 papers, 2013 to 2025). A disorder characterized by behavioral and/or psychological abnormalities, often accompanied by physical symptoms. "We conclude this Perspective with some of the outstanding issues for the field to consider where a multi-systems approach is needed to investigate the complex nature of LHb circuitry interactions with environmental stimuli that predisposes psychiatric disorders." (PMID 35308564, 2022). "Here, we describe how LHb neurons activity can be influenced by excitatory and inhibitory synapses and by neuromodulators, and we discuss the significance of this in relation to the potential role of the LHb in encoding rewarding and aversive stimuli, and in associated psychiatric disorders." (PMID 24379770, 2013). "Our model enables for future investigations into mTBI-induced maladaptive changes in molecular, synaptic and neuronal mechanisms at the level of distinct LHb circuits with implications for psychiatric disorders in mTBI." (PMID 38798343, 2024). "The reviewed data provide a compelling argument that the LHb should be one of the primary targets of therapeutic intervention, such as with psilocybin, for psychiatric disorders that manifest in context memory, motivational impairments, and certain disorders of behavioral control." (PMID 35444521, 2022). "Supporting our hypothesis, improper functioning of the LHb results in impairments in behavior related to response flexibility such as those seen in psychiatric disorders." (PMID 35444521, 2022). "Although LHb neurons also connect with serotonergic raphe nuclei and this LHb–serotonin circuit seems to be important in psychiatric disorders, little is known about how the LHb–serotonin circuit might be associated with depression." (PMID 28420875, 2017). "And, since LHb is highly associated with negative emotional behaviors, our findings could have implication regarding perioperative psychiatric disorders." (PMID 36740262, 2023). "However, the LHb has received considerable attention for its potential role in cognition and pathogenesis of various psychiatric disorders, and since we observed eGFP expression in the LHb, the ChAT-eGFP mouse model could be a potential transgenic model to study further on the habenula complex." (PMID 36650430, 2023). "In summary, given the robust role of the LHb in psychiatric disorders as well as the role of CB1R-mediated regulation of LHb activity, targeting the eCB system for ELS-induced psychiatric disorders is a potential therapeutic option." (PMID 34122037, 2021). "The LHb, VTAGABA, and VPGlu neurons all generate aversion, are activated by aversive stimuli, and are involved in a variety of psychiatric disorders." (PMID 40700490, 2025).
tumor (4 papers, 2015 to 2025). "The NIH3T3 cell line constitutively expressing W4P LHB induced preferential tumor formation in male nude mice over females, as well as having oncogenic potential at a high level, with 95% tumor generation incidence within 4 weeks." (PMID 25645622, 2015). "NIH3T3 cells expressing variant LHB, but not the WT, induced tumor in a nude mouse model." (PMID 25645622, 2015). "Since the expression of LHB and GNRHR is related to NR5A1 in both Subtype 1 sPitNETs and gonadotroph PitNETs, other genes regulate by this TF turn out to be differentially expressed in these tumor types." (PMID 40813692, 2025). "The UMAP plots showed that the LHB, GNRHR, TGFBR3L, FOSB and SCGN genes were highly expressed mainly in the epithelial cells of the normal group, while their expression was low in the epithelial cells of the tumour group." (PMID 39548559, 2024). "LHB and PGR exhibited high expression levels in normal samples and paratumoural regions of tumour samples; however, their expression levels were relatively low in the tumour region of tumour samples." (PMID 39548559, 2024).
cancer (1 paper, 2021). A tumor composed of atypical neoplastic, often pleomorphic cells that invade other tissues. "Furthermore, the contribution of GNRH2, PRLH, GPR156, GRIK5, LHB, and CRHR2 to the neuroactive ligand-receptor interaction pathway are specified in ATLL in consistent with some other cancers." (PMID 34446027, 2021).
infection (1 paper, 2024). The state of being infected such as from the introduction of a foreign agent such as serum, vaccine, antigenic substance or organism. "The LHB level was found to be much higher in hepatitis than in infection phases or healthy blood donors." (PMID 38251353, 2024). "Another study confirmed the value of LHB quantitation as a complementary marker to determine different stages of infection." (PMID 38251353, 2024). "Since heparan sulphate proteoglycans can be found on various cell types, it is now believed that LHB does not express pre-S1 on the surface during the initial infection of a naïve host to avoid ineffective attachment before virions can reach the liver." (PMID 38251353, 2024). "Total HBsAg, LHB and MHB levels were significantly higher in HBeAg-positive than in HBeAg-negative phases of infection, but their proportions were similar." (PMID 38251353, 2024).
LHB also shares sentences with these, for which no sentence is quoted: endometriosis (2 papers); amnesia (1); anxiety disorder (1); atopic dermatitis (1); Azoospermia (1); breast carcinoma (1); central precocious puberty (1); embryonal carcinoma (1); endocrine disorders (1); frontotemporal dementia (1); metastatic disease (1); metastatic melanoma (1); mixed germ cell tumor (1); neurological disease (1); Noonan syndrome (1); Parkinson disease (1); pituitary adenoma (1); polycystic ovary syndrome (1); postpartum depression (1); reproductive diseases (1); social phobia (1); stress-related disorder (1); substance abuse (1); TARP syndrome (1); tendinopathy (1); ZIKV infection (1).